RNU6-239P (RNA, U6 small nuclear 239, pseudogene)
Gene: Small nuclear RNA gene on chromosome 1 (154,295,503 to 154,295,601, forward strand). Ensembl gene ENSG00000212292.
Homologues: Orthologues: dog U6 (67% identical). Paralogues in human: RNU6-121P (94% identical), RNU6-1263P (83% identical), RNU6-41P (83% identical), RNU6-10P (82% identical), RNU6-1122P (82% identical), RNU6-38P (82% identical), RNU6-574P (82% identical), RNU6-618P (82% identical), RNU6-820P (82% identical), RNU6-1060P (81% identical), RNU6-1075P (81% identical), RNU6-1078P (81% identical), and 1286 more.